LINC02912 (long independently transcribed non-coding RNA 2912)
Synonyms: TMEM75; FLJ36105
Gene: Long non-coding RNA gene on chromosome 8 (127,946,559 to 127,948,723, reverse strand). Ensembl gene ENSG00000280055.
Subcellular location: Membrane
Diseases named in the same sentence as LINC02912 in open-access papers:
LINC02912 is named in the same sentence as 3 diseases in open-access papers, as found by Europe PMC text mining. Sharing a sentence is not in itself a finding about the gene and the disease.
LINC02912 shares sentences with these, for which no sentence is quoted: cancer (4 papers); colorectal cancer (1); Dementia with Lewy Bodies (1).